INPP5D (inositol polyphosphate-5-phosphatase D)
Diseases named in the same sentence as INPP5D in open-access papers (continued):
Sharing a sentence is not in itself a finding about the gene and the disease.
cognitive decline (4 papers, 2018 to 2024). "However, caution is warranted, and further studies are necessary to determine whether INPP5D agonism and/or antagonism may prevent or alleviate the synapse loss and cognitive decline observed in AD." (PMID 38016942, 2023). "INPP5D mRNA expression in peripheral leucocytes is elevated in early AD but is decreased with cognitive decline." (PMID 33716646, 2021). "Further long-time follow-up of the participants would be necessary to decipher the correlation between the level of INPP5D mRNA and cognitive decline." (PMID 33716646, 2021).
colorectal cancer (3 papers, 2020 to 2025). A primary or metastatic malignant neoplasm that affects the colon or rectum. "So far, the mechanism(s) by which SHIP1 is upregulated in several solid tumors, especially in colorectal cancer, is speculative, but common mechanisms could include aberrant DNA demethylation of the INPP5D promotor and/or upregulation or downregulation of a transcriptional activator or repressor." (PMID 32679836, 2020).
Hyperglycemia (3 papers, 2016 to 2021). An increased concentration of glucose in the blood. "With OLAN treatment, in addition to its induction of INPP5D, the suppression of AMY2B and GNAI1 are predicted to increase hyperglycemia and decrease insulin sensitivity." (PMID 33302598, 2020).
prostate carcinoma (3 papers, 2016 to 2024). A carcinoma that arises from epithelial cells of the prostate gland. "One notable exception was prostate cancer in which neither of the PGCC signatures but rather the 5-gene core signature of late progeny (FN1, INPP5D, ITGB4, ARHGDIB, IFIT1) was significantly predictive of outcomes." (PMID 38447798, 2024).
B-cell acute lymphoblastic leukemia (2 papers, 2024 to 2025). A neoplasm of lymphoblasts committed to the B-cell lineage, typically composed of small to medium-sized blast cells. "Five mutations of the INPP5D gene in patients with acute lymphoblastic B-cell leukemia were identified in the COSMIC database." (PMID 40725184, 2025). "Four mutations of the INPP5D gene in patients with acute lymphoblastic B-cell leukemia were identified in the COSMIC database." (PMID 38992657, 2024). "Mutations of the INPP5D gene in patients with acute lymphoblastic B-cell leukemia were rare." (PMID 38992657, 2024).
cognitive deficits (2 papers, 2023 to 2024). "Additionally, they showed that INPP5D downregulation restored plaque compaction, and increased microglial motility towards and phagocytosis of amyloid plaques, with a resultant alleviation of cognitive deficits compared to mice expressing normal levels of INPP5D." (PMID 37895194, 2023).
malaria (2 papers, 2023). Malaria is a serious and sometimes fatal disease caused by a parasite that commonly infects a certain type of mosquito which feeds on humans. "Thus, our study reveals the key role of INPP5D in mediating the crosstalk between IFN-I response and autophagy during anti-malarial immune responses, and suggests that INPP5D may be a potential therapeutic target to control malaria." (PMID 40395314, 2023).
tauopathy (2 papers, 2019 to 2024). Neurodegenerative disorders involving deposition of abnormal tau protein isoforms (tau proteins) in neurons and glial cells in the brain. "PS19 Tauopathy mice were crossed with Inpp5d‐haplodeficient (Inpp5d+/−) mice to examine the impact of Inpp5d in tau pathology." (PMID 38923171, 2024). "Therefore, we aimed to investigate the role of INPP5D in tau pathology in the PS19 mouse model of tauopathy." (PMID 38923171, 2024). "However, they require further mechanistic investigations and provide the foundation for further evaluation of therapeutic interventions aimed at INPP5D inhibition, which may benefit tauopathies." (PMID 38923171, 2024).
atherosclerosis (1 paper, 2023). A disease characterized by the build-up of fatty material and calcium deposition in the arterial wall resulting in partial or complete occlusion of the arterial lumen. "Similarly, when querying the liver KDs in the atherosclerosis HMDP liver tissue, we found Cidec is negatively correlated with aortic lesion area as well as numerous KDs including Inpp5d and Nckap1l positively correlated with aortic lesion area." (PMID 38060277, 2023). "Within the shared CAD/atherosclerosis liver network between species, APBB1IP, PTPRC, NCKAP1L and INPP5D were captured as potential novel KDs which again have not been strongly investigated, validated or implicated in CAD previously." (PMID 38060277, 2023).
Cerebral atrophy (1 paper, 2015). Atrophy (wasting, decrease in size of cells or tissue) affecting the cerebrum. "Expression of the top five differentially expressed genes found by GWAS - MS4A6A, CD2AP, INPP5D, MEF2C and CLU – all have good correlation with Braak stage and cerebral atrophy." (PMID 26202100, 2015).
diverticulitis (1 paper, 2024). An infection that develops in the diverticula of the intestinal tract. "Hub genes RASAL3, SASH3, PTPRC, and INPP5D were found to upregulate immune response-associated transcripts in the sigmoid colons of chronic, recurrent diverticulitis patients as identified by Schiefer et al25." (PMID 38831715, 2024). "This built on earlier work, by the same team, which suggested the hub genes RASAL3, SASH3, PTPRC and INPP5D within the brown module eigengene were highly correlated (r = 0.67, P = 0.0004) with diverticulitis." (PMID 38831715, 2024).
Insulin resistance (1 paper, 2020). Increased resistance towards insulin, that is, diminished effectiveness of insulin in reducing blood glucose levels. "With RIS treatment, the decreased expression of AOX3 and increased expression of INPP5D are predicted to contribute to insulin resistance." (PMID 33302598, 2020).
ischemic stroke (1 paper, 2015). A stroke disorder caused by obstruction of blood flow to the brain, due to thrombotic (local blood clot formation) or embolic (due to a blood clot or other material traveling from another site) event. "The INPP5D enzyme regulates myeloid cell proliferation and programming, and its expression correlates with hemorrhagic transformation of ischemic stroke." (PMID 25994285, 2015).
liver fibrosis (1 paper, 2021). "INPP5D (also known as SHIP) could restrain proinflammatory cytokine production and correlate inversely with histological stages of liver fibrosis in vivo." (PMID 34626074, 2021).
lung adenocarcinoma (1 paper, 2024). A carcinoma that arises from the lung and is characterized by the presence of malignant glandular epithelial cells. "Here, we reported a case with concomitant ALK rare double-fusion, namely PLEKHA7-ALK and INPP5D-ALK in a patient diagnosed with lung adenocarcinoma who showed favorable response to alectinib following chemotherapy failure." (PMID 38379102, 2024). "In conclusion, this case report described a novel ALK double-fusion involving PLEKHA7-ALK and INPP5D-ALK in lung adenocarcinoma." (PMID 38379102, 2024). "This is the first case presenting a rare concomitant ALK double-fusion, namely PLEKHA7-ALK and INPP5D-ALK, in a patient with lung adenocarcinoma, who exhibited favorable sensitivity to alectinib." (PMID 38379102, 2024).
myelofibrosis (1 paper, 2025). A partial or complete replacement of the bone marrow stroma by fibrous tissue. "While no clear overall association was found, some candidate genes exhibited concordant changes in DNAm and gene expression, such as hypermethylated and downregulated ZFP36L1, linked to myelofibrosis progression and INPP5D known to be downregulated by JAK2 V617F." (PMID 40319310, 2025).
Onset (1 paper, 2022). The age group in which disease manifestations appear. "INPP5D is expressed at low level in normal brain; however, the AD-associated INPP5D polymorphism (rs35349669) increased INPP5D gene expression in the brain and whole blood in patients with late-onset AD." (PMID 35693341, 2022).
primary immunodeficiencies (1 paper, 2023). "Variants in ICAM1 and INPP5D are reported to be associated with primary immunodeficiencies in HGMD." (PMID 37080976, 2023).
Solid Pseudopapillary Neoplasm of the Pancreas (1 paper, 2016). A low-grade malignant neoplasm that arises from the exocrine pancreas. "Eighteen cases of solid pseudopapillary neoplasms of the pancreas were evaluated for RNA expression levels of FLI1, DKK1, INPP5D (SHIP1), IGFBP3, PBK (TOPK), and BCL9 and BCL9L." (PMID 27539223, 2016).
thyroid cancer (1 paper, 2021). "Mice were treated with doxycycline for one week to develop thyroid cancer, and the expression levels of CCL2, CSF-1, LGALS3BP, INPP5D and CCL7, together with that of the chemokine receptors CCR2 and CSF1R, were measured in cancer specimens by quantitative RT-PCR." (PMID 34299284, 2021).
tumor (61 papers, 2011 to 2025). "In NSCLC, the expression of INPP5D was down-regulated in both tumor tissues and cell lines, and the overexpression of INPP5D suppressed cell growth, migration, and invasion by inactivating PI3K/AKT pathway." (PMID 39176091, 2024). "Post transcriptional regulation of INPP5D (SHIP1) with MicroRNA-155 (miR-155) has shown to impact tumor progression." (PMID 33672717, 2021). "IPMN, accordingly, showed intermediate expression of BCL9L, but instead demonstrated a high expression of the cyclin D1 inhibitor INPP5D, possibly contributing to the better prognosis of this neoplasia compared to PDAC." (PMID 27539223, 2016). "The intermediate β-selection phenotype of Itpkb-loss between those of Pten-loss and Inpp5d/SHIP1-loss raises the possibility that IP3 3-kinases could have tumor suppressor functions by limiting Akt signaling." (PMID 26880557, 2016). "Lastly, in CR-TNBC patient P942, the baseline PDX tumor (BTY14) had high phosphorylation on the shared pTyr sites of SRC, FYN, LCK, YES1, and FGR as well as SFK substrates such as tensin, SHIP-1 (INPP5D), AFAP1L2, paxillin, and PTK2." (PMID 36077757, 2022). "Similarly, the expression of gene markers of tumor-initiating cells (ALDH1A1, CD29, INPP5D) was different between the CL subtype and the other subtypes, including the basal subtype (data not shown)." (PMID 25277734, 2014). "We also found that the mRNA expression levels of INPP5D were down-regulated in LUSC but not in LUAD, suggesting tumor specificity between LUSC and LUAD." (PMID 39176091, 2024).
cancer (42 papers, 2007 to 2025). A tumor composed of atypical neoplastic, often pleomorphic cells that invade other tissues. "Mutations in INPP5D are associated with defects in the immune system and cancer." (PMID 33854600, 2021). "From the MSigDB Cancer Neighbourhood Ontology, we found that the GM-enriched binding windows were in proximity to cancer-associated genes, CD53, VAV1, INPP5D, STAT6, HLA-C, etc." (PMID 25522020, 2014). "Validated miR-155 target genes are present in multiple pathways associated with cancer and cancer progression, including EMT (SMAD5), proliferation (SOCS1, INPP5D, and CSF1R), block of differentiation (SPI1, CEBPB), and apoptosis (CASP3, FADD, APAF1, and FOXO3A)." (PMID 27128908, 2016). "For example, several genes such as DKK1/2, CSNK1A1, INPP5D, and INPPL1 in the cases we discussed in detail are not present on the cancer panels we examined, yet their functional roles in respective signaling pathways are well-documented." (PMID 27245685, 2016).
neurodegenerative disease (4 papers, 2022 to 2024). A disorder of the central nervous system characterized by gradual and progressive loss of neural tissue and neurologic function. "Polymorphisms in the INPP5D gene encoding SHIP-1 have been linked to the development of neurodegenerative diseases." (PMID 37830592, 2023). "The dysregulated genes, otherwise masked by haplosufficiency of Inpp5d, will provide new leads for further investigating their roles in microglial function and neurodegenerative diseases." (PMID 38923164, 2024). "We identified several genes associated with neurodegenerative diseases, including PFN1 and INPP5D, as modulators of phagocytosis in microglia, thus pointing to a possible cellular mechanism by which variants in these genes contribute to disease (Supplementary Discussion)." (PMID 35953545, 2022). "Thus, Inpp5d expression may affect the ability of microglia to clear protein aggregates in other neurodegenerative diseases." (PMID 38923164, 2024).
INPP5D also shares sentences with these, for which no sentence is quoted: infection (22 papers); ileitis (9); myeloproliferative disorder (9); osteoporosis (9); lupus (8); multiple myeloma (8); acute lymphoblastic leukemia (7); inflammation (7); Sepsis (7); breast carcinoma (6); chronic myeloid leukemia (6); colitis (6); autoimmune disease (5); Autoimmunity (5); bacterial infection (5); diffuse large B-cell lymphoma (5); hematopoietic cancers (5); inflammatory bowel disease (5); pneumonia (5); asthma (4); colon cancer (4); erythroleukemia (4); gout (4); lung fibrosis (4); metabolic syndrome (4); myelodysplastic syndrome (4); rheumatoid arthritis (4); Allergy (3); Arthritis (3); hematological malignancies (3).
A further 99 diseases each share a sentence with INPP5D in 3 papers or fewer.